IL6 (interleukin 6)
Diseases named in the same sentence as IL6 in open-access papers (continued):
Sharing a sentence is not in itself a finding about the gene and the disease.
Sepsis (continued). "As the concentration of inoculated E. coli increased, we observed a significant increase in serum IL-6 and TNF-α levels, indicating that adjusting the concentration of E. coli could control the severity of sepsis in our study." (PMID 36685507, 2022). "Interestingly, expression of inflammatory mediators IL-1β, IL-6, TNFα, iNOS, and COX2 decreased in the presence of a mitoNEET inhibitor, NL-1, or upon expression of mitoNEET shRNA, even in the LPS-induced sepsis model." (PMID 35136051, 2022). "Recently, the importance of IL-6 in COVID patients has increased, and the traditional sepsis score parameters do not fully explain or provide answers to all of the concerns raised by the cytokine storm." (PMID 36589200, 2022). "Although it is true that the septic patients had higher IL-6 levels as compared to the non-sepsis group, the difference was not statistically significant." (PMID 35582414, 2022). "This overwhelming immune response from the cytokines, including interleukin-6 (IL-6), interleukin-8 (IL-8), interleukin-1b (IL-1b), macrophage inflammatory protein-1b, and tumor necrosis factor (TNF-a) leads to sequelae of sepsis via capillary leakage and organ failure." (PMID 36004958, 2022). "Furthermore, compared with the sham group, Western blotting analysis of the collected lung tissues revealed that the expression levels of IL-6 and TNF-α proteins were increased in the model sepsis group." (PMID 36685507, 2022). "Additionally, immune trained monocytes from sepsis patients upregulated TNF–α and IL–6 upon LPS stimulation." (PMID 35693816, 2022). "Low levels of RBCs and high levels of IL-6 and IFN-γ may contribute to the expansion of CD71+ erythroid cells in sepsis." (PMID 35251018, 2022). "Among appropriate for gestational age infants without sepsis, IL-6 and leptin were strongly correlated (R=0.6, P<0.001)." (PMID 35197933, 2022). "The IL-6 and PCT tests have similar diagnostic values in distinguishing sepsis from non-infectious systemic inflammatory response syndrome." (PMID 36249210, 2022). "The transcription factor, HIF-1α is induced in monocytes from patients with sepsis, and upregulated IRAK3 mRNA and protein expression between 0.5h to 24h as well as reducing TNF-α and IL-6 expression at IT and LT in in vitro monocytes challenged with endotoxin." (PMID 35167625, 2022). "Absence of IL‐6 → ↑ hepatic dysfunction and mortality in sepsis ↓ IL‐6 activity → failed bile acid and organic anion clearance, enhanced hepatocellular injury, failed regeneration, poor outcome." (PMID 35774351, 2022). "Rhamnetin injection in the mouse model of sepsis downregulated TNF-α by 93.2% and IL-6 by 84.5%." (PMID 36361685, 2022). "Finally, we identified that IL-6 and TNF-α protein expression levels were significantly elevated in the sepsis group by immunohistochemistry and Western blotting analysis of renal tissues compared to the sham group." (PMID 36685507, 2022). "The levels of IL-6, TNF-α, IL-1β, CD4+, and CD8+ in the three groups of patients were compared to analyze the correlation of blood glucose levels with inflammatory response and immune indicators in patients with sepsis." (PMID 35664433, 2022). "In addition, MSCs were able to reduce the levels of pro-inflammatory cytokines such as IL-1β, IL-6 and TNF-α and elevate the levels of anti-inflammatory cytokines such as IL-10 and TGF-β in the circulation of aged sepsis model rats." (PMID 35197984, 2022). "When sepsis develops, inflammatory molecules such as TNF-α and IL-6 may bind to signal transducers and activators of transcription 3 (STAT3) due to early inflammation in the body." (PMID 35890197, 2022). "Low levels of RBCs and high levels of IL-6 and IFN-γ may contribute to the expansion of CECs in sepsis." (PMID 35251018, 2022).
Sepsis (continued). "Moreover, some sepsis treatment strategies might be beneficial in sepsis from Candida and Klebsiella as the increased serum IL-6 in our mice might be attenuated by the interference of IL-6 and/or Janus kinase-signal transducer and activator of transcription (JAK/STAT) pathway." (PMID 35806054, 2022). "Therefore, we assessed the gene expression of pro-inflammatory cytokines IL-1β, IL-6, TNF-α, and keratinocyte chemoattractant (KC), which are increased during sepsis." (PMID 35628471, 2022). "However, treatment with ICOS-Fc significantly decreased IL-1β and TNF-α in WT mice and IL-1β, IL-6 and IL-10 in ICOS-/- mice indicating that ICOS-Fc substantially downmodulates the cytokine storm in sepsis." (PMID 36119089, 2022). "From a mechanistic perspective, sepsis is primarily characterized by excessive inflammation response and unrestrained oxidative stress, resulting in severe inflammatory tissue damage driven by TNF-α, IL-6, and other proinflammatory cytokines." (PMID 35978995, 2022). "Furthermore, inflammatory cytokines (TNF-α, IL-1β and IL-6) in plasma and bronchoalveolar lavage fluid (BALF) were reduced, representing sepsis-induced inflammatory response was attenuated." (PMID 36030287, 2022). "The sepsis-induced activation of p38 MAPK was paralleled by a massive increase in the systemic levels of proinflammatory cytokines, such as TNF-α, IL-1β, IL-17 and IL-6, as well as the anti-inflammatory cytokine IL-10." (PMID 35178052, 2022). "Conversely, several of these cytokines (IL‐1β, IL‐6, TNF‐α, CXCL1) were significantly elevated in AZ106‐treated mice compared to those subjected to CS alone, indicating a potential role for P2X7R in the modulation of the inflammatory response during sepsis." (PMID 35668576, 2022). "A meta-analysis of an animal model of sepsis with resveratrol intervention suggested that resveratrol can reduce the sepsis-induced inflammatory response by reducing TNF-α, MDA, and IL-6 levels; increasing IL-10 levels; and improving mean arterial pressure, thus improving the microcirculation." (PMID 35222035, 2022). "IL-6 levels correlate with plasma ADMA, severity of sepsis and mortality." (PMID 35962414, 2022). "In fact, LPS-induced endotoxemia induces arterial hypotension, lactic acidosis, tachycardia, and specific temporal elevations of circulating levels of tumor necrosis factor (TNF)-α, interleukin (IL)-6, and high mobility group box (HMGB)-1, which are important features of sepsis and septic shock." (PMID 35163089, 2022). "Significantly elevated circulating IL6 levels were observed in non-sepsis trauma patients (p < 0.0001) and sepsis trauma patients (p < 0.0001) in comparison with healthy controls." (PMID 36471343, 2022). "In these patients, receiver operating curve (ROC) analysis showed a lower diagnostic sensitivity and specificity of clusterin for the detection of sepsis compared with interleukin-6 and procalcitonin (data not shown)." (PMID 36553017, 2022). "The AST could affect the TNF, PI3K, and MAPK pathway cascade responses centred on IκBα and NF-κB, attenuate the expression of IL-6 and MMP9, and interfere with the inflammatory response during sepsis." (PMID 35399630, 2022). "IL-6 at birth was not significantly different between BCxS and CS but higher than in rule out sepsis and no antibiotics." (PMID 35820876, 2022). "A rise in TGF-β and IL-6 levels on the first day of sepsis has been documented in nonsurvivors compared to survivors." (PMID 36010680, 2022). "This nano drug can improve the overall survival rate of sepsis caused by Gram-negative bacteria and inhibit inflammatory factor (TNF-α And IL-6) and inhibit E. coli." (PMID 36110326, 2022). "In particular, its increased expression during sepsis contributes to the suppression of macrophage migration, as well as a decrease in NFKB1 transcriptional activity and the downstream cytokines TNF-α and IL-6." (PMID 36670868, 2022).
Sepsis (continued). "LFM-A13 also reduced the histopathological changes and cellular apoptosis in intestinal tissues, inhibited the inflammatory cytokines IL-4, IL-6, and TNF-α in serum and intestinal tissues, and significantly inhibited the increase in intestinal MPO activity induced by burn sepsis." (PMID 35280898, 2022). "Activated macrophages express many pro-inflammatory cytokines such as IL-6 and TNF-α, which could promote the inflammatory response of sepsis." (PMID 35572571, 2022). "While in the non-bloodstream and non-ARDS group, “IL-6 IL-10 ratio” was higher in G- sepsis patients but without statistical significance." (PMID 36544765, 2022). "In sepsis no large scale studies have been performed on blocking IL-6 but tocilizumab has proven to attenuate infection and improve survival in an animal model of sepsis." (PMID 35548445, 2022). "Moreover, they have been proven to induce systemic inflammatory response syndrome (SIRS) (e.g., leukopenia, thrombocytopenia, increasing the IL-6 and TNF-α concentration or sepsis)." (PMID 35283837, 2022). "The median concentrations of TNF-α, IL-6, IL-8, MCP-1, and the chemokine CXCL1 in glioblastoma cyst fluid were far higher than previously published serum values for SARS covid-19 patients, patients with sepsis, and healthy controls." (PMID 35965529, 2022). "We established a murine sepsis model by CLP with wild-type and IL-6 KO mice in the present study." (PMID 35528525, 2022). "In addition, silymarin (100 mg/kg, i.p.)enhanced overall survival following sepsis compared to septic group (80% vs. 20%) in rat model, as well as improved hepatic and renal function parameters and decreased MDA, nitrite/nitrate, IL-6, and TNF-α levels." (PMID 36588685, 2022). "A prospective study evaluated IL-6, HMGB-1, and neutrophil gelatinase-associated lipocalin (NGAL) in 14 septic patients and 16 patients without sepsis admitted to the ICU." (PMID 34991675, 2022). "However, the concentration of IL-6 and IL-1β of different genotypes was similar in the T2DM combined with sepsis group and control group." (PMID 35960063, 2022). "Most G+ NPMODS sepsis patients experienced significantly higher levels of pro-inflammatory IL-6 without relevant IL-10 elevation." (PMID 36544765, 2022). "A decrease in IL-6 predicts the success rate of antibiotic therapy for sepsis in nonsurgical patients." (PMID 36249210, 2022). "Another previous study also showed that PCSK9 over-expression could increase plasma IL-6 concentration, while knockout of PCSK9 could decrease plasma IL-6 levels and attenuate organ inflammatory response in the mouse septicemia model." (PMID 35252378, 2022). "In both NPMODS and non-NPMODS subgroups, median levels of IL-6 and IL-10 in patients with G- sepsis were higher than those with G+ sepsis." (PMID 36544765, 2022). "For example, long non-coding metastasis-associated lung adenocarcinoma transcript 1 (lnc-MALAT1) and micro RNA (miR)-125a were increased in sepsis patients compared with healthy controls and positively correlated with APACHE-II score, SOFA score, serum creatinine, CRP, TNF-α, IL-1β, IL-6, and IL-8." (PMID 34991675, 2022). "In our previous study of 102 critically ill severe sepsis and/or trauma patients with MODS, we aimed to assess the prognostic value and daily trend of IL-6, nCD64 expression, CRP and lipopolysaccharide-binding protein (LBP) in relation to the outcome measure of hospital mortality." (PMID 34945111, 2021). "In the early stage of sepsis, macrophages promote host defense by eliminating invading pathogens or damaged tissues and releasing abundant amounts of proinflammatory cytokines, such as TNF-α, IL-1β, and IL-6." (PMID 34220338, 2021). "Newer biomarkers like procalcitonin-Interleukin-6 can better predict septicemia, however these are costly and not extensively used." (PMID 35199783, 2021).
Sepsis (continued). "Currently, procalcitonin (PCT), interleukin-6 (IL-6), heparin-binding protein (HBP), C-reactive protein (CRP), serum resistin, and other indicators can be used to assess the severity and prognosis of sepsis." (PMID 34514164, 2021). "Besides, it also restores the balance of CD4+/CD8+ and Th1/Th2 ratio and reduces the concentrations of IL-6, TNF-α, and HMGB1, thus inhibiting the systemic inflammatory response induced by sepsis to alleviate lung injury." (PMID 34057015, 2021). "Sepsis patients with encephalopathy have higher IL-6 levels in cerebrospinal fluid than non-septic controls without encephalopathy." (PMID 34711216, 2021). "In this study, several inflammatory biomarkers, including HBP, CRP, IL-6, N%, PCT, and D-dimer, could significantly predict sepsis." (PMID 34778149, 2021). "CB1 blocking does not change sepsis-induced leukopenia, neutrophil migration, or plasma IL-6 levels." (PMID 34087197, 2021). "Thus, biomarkers of inflammation or infection, such as procalcitonin (PCT), C-reactive protein (CRP), interleukin-6 (IL-6), neopterin, and pro-adrenomedullin (pro-ADM), have a significant role in the diagnosis and management of sepsis." (PMID 33810263, 2021). "Cytokine levels increased in both groups after sepsis onset (wt: IL-6, p = 0.004; TNF-α, p = 0.008; IL-10, p = 0.008; fD−/−: IL-6, p = 0.001; TNF- α, p = 0.002; IL-10, p = 0.001), whereas IL-6 levels were higher in fD−/− mice compared to wild-type at 3-h (p = 0.012) after CLP." (PMID 34396466, 2021). "IL-6 was significantly higher in sepsis than MIS-C (p < 0.01), while CRP and PCT were non-statistically different." (PMID 34869111, 2021). "Furthermore, IL-6 enables earlier diagnoses of SIRS, and IL-6 levels reflect the severity and outcome of sepsis." (PMID 34749673, 2021). "IL-6 and TNF-α are released by the activated neutrophils and macrophages, and are well recognized as pro-inflammatory cytokines and biomarkers for the diagnosis of sepsis." (PMID 34721017, 2021). "IL-6 may predict organ failure in critical illness earlier than SOFA and may improve mortality discrimination of clinical judgment in patients with sepsis." (PMID 32034914, 2021). "This difference also appears in serum IL-6 values between the burn patients with and without sepsis." (PMID 33654698, 2021). "The areas under the receiver operating characteristic curves (AUROCs) for sepsis discrimination with WRS, procalcitonin (PCT), CRP, and IL-6 are 0.864, 0.727, 0.625, and 0.651, respectively, indicating that WRS has better predictive value than other clinical factors of sepsis." (PMID 33926067, 2021). "We detected a prominent effect of AE administration downregulating BALF levels of CXCL-1 (P < 0.05), CXCL-8 (P < 0.01), IL-6 (P < 0.05), IL-10 (P < 0.01), and TNF-α (P < 0.001) and upregulating BALF levels of IL-10 (P < 0.05) and IL-1RN (P < 0.05) during sepsis." (PMID 34493741, 2021). "Both experimental and clinical studies have shown that there is a significant decrease thanks to plasmapheresis in TNF-alpha, interleukin-6 (IL-6), and endotoxins levels, which play a role in the pathogenesis of systemic inflammatory response syndrome (SIRS) and sepsis." (PMID 33628651, 2021). "In contrast, CLP-induced sepsis resulted in increased expression of pro-inflammatory genes (Il6, Ltf, and Lbp) in BAT, without affecting expression of genes encoding for thermogenic activity." (PMID 34322037, 2021). "IL-6, IL-12, IL-1β and TNF-α are important inflammatory cytokines in sepsis." (PMID 33995024, 2021). "The combination of PCT, IL-6, lactate and the SAPS-2 score had the highest AUC on 1-month mortality in patients with sepsis in the ED, but this finding may be overfitted and requires external validation." (PMID 34120605, 2021). "The levels of IL-6 in healthy people are extremely low, generally not exceeding 7 pg/mL, whereas the levels of IL-6 in the serum of sepsis patients increases rapidly in the early stage of infection, and can reach a peak within 2 h." (PMID 33902476, 2021).
Sepsis (continued). "Regarding the intermediate monocytes, such an exaggerated elevation has been shown in severely injured patients 48 h post-trauma and under inflammatory conditions such as sepsis or bacterial and viral infections, paralleled by sequestration of high amounts of TNF-α, IL-1β, and IL-6." (PMID 34575249, 2021). "During sepsis, LPS/LTA can activate the MAPK signaling pathway, and further accelerate the production of proinflammatory cytokines, such as IL-1β, IL-6, and TNF-α, which form the cytokine cascade, and eventually leads to cell apoptosis and multiple organ dysfunction." (PMID 34483941, 2021). "Consequently, we measured the production of IL-6, TNF-α and IL-1β in sepsis patients and healthy controls and in PBMCs under in vitro LPS stimulation to investigate the effect of the NLRP3 29940 G>C variation on the production of these related cytokines." (PMID 34172780, 2021). "Recently, the role of IL-6 has become a key marker in COVID patients, and the classical parameters used for sepsis score do not clarify or answer some of the questions posed by the cytokine storm." (PMID 33685484, 2021). "We found the opposite course of IL-6 in spleen and plasma after 6 h in cecal slurry induced sepsis model, which has not been seen in other study." (PMID 33413559, 2021). "Some laboratory parameters, including serum ferritin, TG, sCD25, IFN-γ, IL-6, IL-10 and TNF-α, could reflect the level of “inflammatory storm, which lead to the “sepsis-like symptoms” and organs injuries in HLH." (PMID 35127776, 2021). "Moreover, at the transcriptional level, Jun can enhance the production of inflammatory cytokines in sepsis-induced ALI, and STAT3 activated by IL-6 also contributes to the progression of ALI." (PMID 34721017, 2021). "Butyric acid reduces the nuclear NF-κB activity, IL-6 and TNF-α levels, and lung tissue neutrophil infiltration by inhibiting the expression of high mobility group protein 1, TLR4, or histone deacetylase to reduce sepsis-related ALI." (PMID 35003009, 2021). "We hypothesised that baseline plasma levels and kinetics of IL-6, IL-8, HBP and MPO differ depending on the phase of sepsis." (PMID 33461369, 2021). "Findings pertaining to the therapeutic utility of IL-6 inhibition in S-AKI remain mixed, suggesting that processes upstream of IL-6 may be responsible for triggering the deleterious effects in sepsis and S-AKI." (PMID 33736691, 2021). "Overall, all patients had elevated TNF-a and IL-6 levels at initial screening, and most had elevated IL-1β and IL-18, while some had elevated IFN-γ; however, a gradual decrease in levels of all of the cytokines studied was observed upon resolution of sepsis." (PMID 34659208, 2021). "Indeed, the harmful effect of IL-6 has been shown in different models of AKI, including ischemic and sepsis-induced AKI." (PMID 33804100, 2021). "In addition to treating uveitis, ruxolitinib was reported to protect mice from LPS-induced sepsis by suppressing nitric oxide production and the expression of iNOS, TNF-α and IL-6." (PMID 34361917, 2021). "However, it is important to acknowledge that in the present work we found higher IL-6, IL-8, IL-1 β and TNF- α levels, compared and consistent to those commonly described for sepsis." (PMID 34460840, 2021). "The levels of cytokines IL-1β, IL-6, IL-8, MCP-1, and IL-10, and of plasminogen activator inhibitor 1 (PAI-1), were reported to be increased over the acute phase and that IL-6, IL-8, MCP-1, and IL-10 formed a cytokine network in the acute phase of sepsis." (PMID 34654467, 2021). "However, the ability of HBP to predict progression to sepsis in children with severe CAP was inferior to PCT, D-dimer, CRP, IL-6, and N%." (PMID 34778149, 2021). "According to some literatures on NAFLD, some immune-related loci associated with NAFLD could exhibit some level of pleiotropy influencing sepsis with genes of CD14, IL-6, MIF, TLR4, and TNF." (PMID 34938184, 2021).